TNF (tumor necrosis factor)
Diseases named in the same sentence as TNF in open-access papers (continued):
Sharing a sentence is not in itself a finding about the gene and the disease.
infection (continued). "To assess the expressions of inflammatory cytokines following infection with DM-C, we quantified the amount of representative proinflammatory cytokines, including tumor necrosis factor-alpha (TNF-α), interleukin-1β (IL-1β), and IL-6, in the bronchoalveolar lavage fluid (BALF) of infected mice." (PMID 24098364, 2013). "However, to control an acute infection by virulent M. tuberculosis the amplification loop provided by IL-1β through upregulation of TNF in infected macrophages in vitro and here in vivo, seems to be necessary." (PMID 25400917, 2013). "Thus, in contrast to TNF, which is essential for the early control of infection by either virulent or attenuated mycobacteria, IL-1 pathway is not central for controlling less virulent mycobacteria such as M. bovis BCG." (PMID 25400917, 2013). "Second, since TNF-α is induced early during the infection, this may serve as an early biomarker of disease development." (PMID 23483844, 2013). "Several studies have suggested that a balance of TNF-α and IL-10 may be necessary for controlling infection while at the same time preventing severe host tissue damage during Mtb infection." (PMID 23869227, 2013). "This may also be related to the multifold source of TNF, the TNF of macrophage/neutrophil origin being crucial for the immediate response, while T-cell derived TNF is important at later stages of the infection." (PMID 25400917, 2013). "Interestingly, in vivo treatment of Balb/c mice with an anti-murine TNFα monoclonal antibody reversed resistance to infection and the anti-TNFα-treated mice exhibited higher bacterial loads in the lung." (PMID 23745124, 2013). "In the present study, transcript levels in rabbit lungs were measured at 3 hours post-infection, whereas protein and transcript levels of TNF-α and CCL-2 were determined at 7, 14, 21, 28 and 60 days in infected mice or 24, 48, 72 and 96 hours in Mtb-infected human PBMC, in other published reports." (PMID 23958185, 2013). "Do TNF-α and IL-10 processes also affect infection outcomes?" (PMID 23869227, 2013). "The Hp1-1 type was associated with the pro-inflammatory cytokines TNF and IFN-γ both ex vivo and in vitro which could help Dogon individuals to clear the infection, since they showed initially lower levels of these cytokines in their blood." (PMID 24274254, 2013). "T lymphocytes of volunteers successfully infected with either NF135.C10 or NF54 showed similarly increased IFN-γ, tumor necrosis factor, and interleukin 2 recall responses 35 days after infection and the same kinetics for both homologous and heterologous stimulation." (PMID 23186785, 2013). "Infection with E. coli induced a robust TNF-α production, peaking 4 hours p.i.." (PMID 23349721, 2013). "However, tumor necrosis factor-α production by macrophages was the same after infection with mutant or wild-type strains." (PMID 24039915, 2013). "However, it is uncertain if the low level of TNF-α in the spleen directly contributed to the subsequent CNS infection and the neuropathogenesis during JaTH160 infection." (PMID 23940775, 2013). "Alternatively, the infection of macrophages or microglia may enhance the release of pro-inflammatory cytokines such as tumor necrosis factor (TNF-α) and IFN-δ, which are toxic to neurons." (PMID 23620748, 2013). "We previously reported that BALB/c mice infected by the intratracheal route with a high dose of the drug-sensitive H37Rv strain, showed an early high production of antimicrobial peptides and Th1 cytokines, which together with high levels of TNF-α were proposed to temporarily control the infection." (PMID 23555622, 2013). "In the current study, it was found that infection of BALB/c mice with P. berghei K173 caused marked increases in plasma levels of pro- and anti-inflammatory cytokines including IL-5, IL-10, IL-12, IL-13, IFN - γ, and TNF." (PMID 24180253, 2013). "The kinetics of resolution of infection in TNF-α−/− mice was comparable to that in WT mice." (PMID 23483844, 2013).
infection (continued). "Inoculation with viable S. aureus in WT mice induced rapid elevation of TNF-α in the livers and blood at 6 h post-infection; thereafter, the TNF-α levels gradually diminished and were barely detectable at 3 d post-infection in livers and at 1 d post-infection in blood." (PMID 24058538, 2013). "PP2A involved the regulation of p38MAPK activation and TNF-alpha production in H9N2/G1 infection." (PMID 23549267, 2013). "In addition, MPXV infection impaired NK cell degranulation and ablated secretion of interferon-γ and tumor necrosis factor-α." (PMID 24147080, 2013). "Other shortcomings of anti-TNF-α therapies include increased rates of infection and malignancy." (PMID 23945080, 2013). "Although treatments for RA targeting TNFα or IL-1β have proved effective for many patients, there are still some problems to be solved – such as the nonuniversal adequacy and maintenance of response and risks of adverse effects like infection and malignancy." (PMID 24314202, 2013). "It is produced almost exclusively in hepatocytes in response to inflammatory cytokines, such as intereukin (IL)-1, tumor necrosis factor (TNF)-α and, in particular, IL-6, within a few hours following insults such as infection, trauma or cardiovascular diseases." (PMID 24255664, 2013). "Moreover, T-bet+ Th1 cells from WSX-1−/− mice produced significantly more IFN-γ on a per cell basis (as measured by mean fluorescence intensity (MFI) of IFN-γ expression) on days 9, 11 and 14, and significantly more TNF on day 14 of infection." (PMID 23593003, 2013). "DC activation was further confirmed by IL-6 and TNF-α secretion upon EV1 infection." (PMID 23638101, 2013). "Early infection cytokines interleukin 6 (IL-6) and tumor necrosis factor (TNF), which are both secreted by macrophages, showed a statistically significant increase (P <0.05 by Student’s t-test) in the bgh lung as early as day 1, indicating the onset of an inflammatory response." (PMID 24360193, 2013). "In this case, therefore, we speculate that a chronic infection in the subconjunctival space is prolonged due to the increased vulnerability to infection by the anti-TNF-α drug administration, which led to focal scleral necrosis subsequently." (PMID 23738990, 2013). "Contrary to the early expression pattern of IL-6 and MCP-1, TNFα expression was extended for a few more days, thus overlapping with monocyte recruitment to the infection sites, suggesting that monocytes may contribute to TNFα production as well." (PMID 22496642, 2012). "In addition, splenocytes from both groups produced expressive and equivalent levels of IFN-γ and TNF after 9 days of infection." (PMID 22348160, 2012). "However, both FasL and TNF-α were induced profoundly in response to pH1N1 infection, while the change of TRAIL was mild." (PMID 22279582, 2012). "Interestingly, IL-10−/− mice exhibited decreased frequencies of both IFN-γ+ and TNF-α+ CD8+ T cells on day 7 post infection." (PMID 22880122, 2012). "Since MCP-1 plays a role in the recruitment of monocytes and macrophages to sites of infection and macrophages are the main producers of TNF, we speculate that both cell types can stimulate each other." (PMID 22393384, 2012). "The average TNF-α plasma levels increased in both groups post infection." (PMID 22533922, 2012). "In this malarial model, all the pro-inflammatory cytokines, TNFα, IFNγ, IL-1, IL-6 and IL-18 and the anti-inflammatory cytokine IL-10, were significantly elevated in the plasma throughout the infection with the highest level recorded during the late critical stage." (PMID 23323093, 2012). "Peritoneal macrophages stimulated with any of the three TLR agonists exhibited dramatically increased TNF and IL-6 levels at one, three and five days after infection with P. yoelii 17XNL or 17XL, which was consistent with the response of macrophages to pRBC lysate." (PMID 22463100, 2012).
infection (continued). "Moreover, except for MIP-2, concentrations of TNF-α, IL-1β and KC in the lung homogenates obtained 24 hours after infection with serotype 3S." (PMID 22721450, 2012). "We asked if the deficiency of memTNFΔ1–12 KI mice was due to reduced number of macrophages or to a differential expression of transmembrane TNF on macrophages and assessed the total number of CD11b+ and CD11b+/TNF+ cells in spleen before and after the infection." (PMID 22666310, 2012). "IL-6 and TNF are critical inducers of the acute phase response to infection, leading to the hypothesis that EP67 could act as a solo therapeutic agent." (PMID 22792270, 2012). "Neuronal TNF-overexpression combined with BDV-infection leads to cytokine up-regulation, CNS inflammation and glial cell activation and confirmed the presensitizing effect of elevated cytokine levels for the development of spontaneous epileptic seizures when exposed to additional infectious noxi." (PMID 22848506, 2012). "Thus, increased serum levels of TNF were correlated with the severity of disease post-infection in both NFATp−/− mice and WT mice, and the higher TNF levels in NFATp−/− mice were consistent with their more rapid disease progression and mortality." (PMID 22844476, 2012). "We evaluated TLR2/1L-induced innate immune cytokines e.g. TNF-α, IL-1β, IL-6, IL-23 and IL-12, known to be critical players in the control of Mtb infection, and chemokines such as Gro-α and IL-8 that are required for cell recruitment to the site of infection." (PMID 22866178, 2012). "However, it is possible that TNF-α production in DCs after RB51 infection plays a regulatory role in DC cell death." (PMID 22927979, 2012). "As seen during the natural infection, Shigella infection of rabbit ileal loops led to a large increase in mRNA abundance for the pro-inflammatory cytokines IL-1β, TNF- α, IL-6, IL-4, IFN-γ and IL-8, highlighting the similar cytokine response elicited in the two systems." (PMID 22675469, 2012). "TNF-α directly effects immune cell recruitment by upregulation of endothelial adhesion molecules and induction of chemokine production which further recruit leukocytes to the site of infection." (PMID 23110184, 2012). "FV3 infections of adult frogs elicited rapid increases in the gene expression of pro-inflammatory cytokines such as tumor necrosis factor alpha (TNF-α) and interleukin-1β (IL-1β), which are known to target macrophage lineage cells and orchestrate robust innate immune processes." (PMID 22852041, 2012). "Thus TLR4- and TNF-α-dependent functions, such as efficient phagocytosis and killing, appear to be sufficient to prevent lethal infection by RB50ΔsigE in Rag1−/− mice." (PMID 22897969, 2012). "In addition, Th1 cells produce interleukin (IL)-2, interferon (IFN)-γ, and TNF-α, that promote inflammation and cell-mediated immunity in an attempt to control infection." (PMID 22530132, 2012). "Because the infection with high-virulence strains of P. gingivalis may generate a large amount of lipopolysaccharide and TNF-α, it may result in inflammation of not only the local gingiva, but also involve other systemic organs." (PMID 22340817, 2012). "Our results showed that SGE could decrease the pro-inflammatory cytokine TNF-α and IL-1β mRNA levels in lung 5 days after infection." (PMID 23227098, 2012). "In addition, infection of RANKL-primed macrophages with P. gingivalis induced osteoclastogenesis in the presence of neutralizing antibody against TNF-α." (PMID 22723864, 2012). "Explant infection with wild-type Merlin at a tenfold lower multiplicity of infection (0.02 pfu/ml), caused a significant positive correlation between increased explant infection and upregulation of MCP-1 and TNF-α expression (p = 0.0001 and p = 0.017)." (PMID 23300810, 2012). "The production of TNF-α was inhibited at 24 h post S2308 infection." (PMID 22927979, 2012).
infection (continued). "Thus, infection of human and mouse MΦ as well as human and mouse DCs in vitro stimulates TNF and IL-12 transcription and secretion as well as maturation of DCs, as shown for Mtb, M. bovis, BCG and M. avium infections." (PMID 22880012, 2012). "In the acute situation, local production of TNF-α have a clear positive action increasing the expression of adhesion molecules on the vascular endothelium to allow immune cells, as macrophages and neutrophils, to reach the sites of tissue damage or infection." (PMID 23133455, 2012). "Acute CVB3 infection leads to a robust inflammation in cardiac tissue of wildtype mice, which is demonstrated by high numbers of infiltrated inflammatory cells and highly increased expression of proinflammatory cytokines such as IL-1β, IL-6, and TNF-α 10 days after infection." (PMID 22675647, 2012). "Interestingly, RANTES, TNF-α and IL-10 levels were similar in all experimental groups by day 3 post infection." (PMID 23209745, 2012). "Several studies on L. major using models of infection in BALB/c and C57/BL6 mice have shown a good prognosis associated with immune responses that are predominantly Th1 as determined by the production levels of IL-12 and TNF-α cytokines." (PMID 22792440, 2012). "The objective of the present study was to determine whether there was an association between polymorphisms of TNF, LTA, IL1B, IL6, IL8, and CCL1 and the infection and severity of the illness caused by the pandemic A/H1N1 in Mexico in 2009." (PMID 23148654, 2012). "Analysis of the expression of IFN-γ and TNF-α by ICS also revealed that after experimental infection or immunization with AdASP-2 vaccine, the majority of specific T cells were a population of multifunctional T cells that mobilized surface CD107a and expressed both cytokines." (PMID 22615561, 2012). "By eliciting the production of TNF-α, Mtb may gain a capability to penetrate alveolar epithelium after infection." (PMID 23213508, 2012). "While TNF-α and IFN-γ may have a protective effect or stimulate protective responses, their concentrations may be linked to the severity of the infection and the amount of mycoplasma in the host." (PMID 22533922, 2012). "Macrophages are also major sources of pro-inflammatory and immunoregulatory cytokines in response to infection, including tumor necrosis factor (TNF)-α, interleukin (IL)-1 and IL-12, and have an important role in orchestrating the innate and adaptive immune response." (PMID 22829768, 2012). "Whether this TNF/IL-10 imbalance results from an intrinsic incapacity of SMA patients to produce IL-10 or from an IL-10 unresponsiveness to infection is unknown." (PMID 22853732, 2012). "At the same time, this sequence of events could suggest a preceding infection or inflammatory condition that might have promoted both systemic and intraplaque TNF-α synthesis." (PMID 23316287, 2012). "Consequently, secretion of IL-12 and TNF-α proinflammatory cytokines in BaΔwadC-infected BMDC at 24 h post-infection reached intermediate levels between those of Ba-parental and S. Typhimurium." (PMID 22589715, 2012). "Similarly, the TNF-α levels in the serum of db/db mice were significantly higher than that in the WT mice at day 6 after infection (p<0.05)." (PMID 22953001, 2012). "This might indicate that IE1-mediated changes on MKP-1 acetylation become apparent at later stages of the infection and could therefore have a role in the late phase of replication, complementing other viral factors interfering with TNFα action, such as M45." (PMID 22952450, 2012). "Moreover, between 3–5 days after infection, the levels of IL-12p70, TNF-α and IL-6 were higher in mice immunized with one of the antigens than in mice immunized with both DnaK and Tul4, a pattern similar to that seen with the other cytokines assessed." (PMID 23209745, 2012).
infection (continued). "Modelling acute clinical infection using ex vivo placental explant histocultures showed infection with CMV laboratory strain AD169 (0.2 pfu/ml) caused significantly elevated expression of MCP-1 and TNF-α compared with uninfected explants (p = 0.0003 and p<0.0001) (n = 25 per group)." (PMID 23300810, 2012). "Similarly, children who recover from natural infection with the virus show significant amounts of TNF-α production, suggesting that innate immunity plays a major role in the response to Chandipura virus." (PMID 22642811, 2012). "An increase of TNF-α in the plasma was observed in most of the animals following infection, which supports the hypothesis that TNF-α mediates inflammation in CBPP." (PMID 22533922, 2012). "TNF-α, is an important multifunctional cytokine secreted by macrophages, T-lymphocytes, fibroblasts and keratinocytes with wide-ranging biological effects of protection from infection, surveillance against tumors and stimulation of inflammatory responses." (PMID 23284977, 2012). "Interestingly, SFV-NS2B3-WT induced significantly higher expression of TNFα at early times post-infection compared to SFV-NS2B3-S135A control." (PMID 23055924, 2012). "Furthermore, MVA infection induces pro-inflammatory cytokines such as TNF-α, type I interferons and chemokines like CCL2 that attract leucocytes to the site of inoculation." (PMID 22396645, 2012). "Another interesting possibility is that priming of cells during in vivo OT infection may be enhanced by cytokine signaling through positive feedback loop via the production of proinflammatory cytokines such as TNF-α." (PMID 22723924, 2012). "Considering the potential of endosomal TLR signals to induce proinflammatory cytokine expression, UNC93B1 deficient 3d mice were first assessed for systemic IFN-α, IFN-γ, IL-12 and TNF-α production during early infection with a moderate (5×104 PFU) dose of MCMV." (PMID 22723955, 2012). "Why does the RB50ΔsigE mutant spread systemically and cause lethal infection in TLR4def and TNF-α−/− mice, but not Rag1−/− mice?" (PMID 22897969, 2012). "However, both Mph1 and Mph2 phenotypes released comparable amounts of TNFα, IL-12p40 and IP-10 after infection with H3N2, in marked contrast to differential responses to LPS-stimulation." (PMID 22238612, 2012). "Wild-type mice were resistant to M. bovis BCG infection; one out of 14 (93% survival) memTNFΔ1–9,K11E KI mice died, whereas 7 out of 10 (30% survival) memTNFΔ1–12 KI mice succumbed to the infection with loss of body weight, and all TNFR1/TNFR2 −/− and TNF−/− mice died." (PMID 22666310, 2012). "The status of TNF in the context of NK cell activation was explored in the current study since these cells have been reported to be early producers of the cytokine after infection." (PMID 22316273, 2012). "In addition, macrophages, which have been primed with Th1 cytokines (IFN-γ) and other proinflammatory cytokines (GM-CSF, TNF-α, etc.)generated by NK cells and macrophages, produce IL-10 during infections with mycobacterial organisms." (PMID 22666284, 2012). "However, the CD14+/TNF-α+ lung cell population at 16 weeks of infection was moderately higher than that of 4 and 8 weeks." (PMID 22645653, 2011). "A higher proportion of the TNF-238A allele among patients when compared to controls was demonstrated for various other infectious diseases such as infection with Chlamydia trachomatis, although these findings were not statistically significant." (PMID 21408088, 2011). "This limited inflammation was similar to that observed in this infection model in TNFα-/- mice." (PMID 22163046, 2011). "The impaired expression of IFN-α and TNF-α of DCs following the JEV P3 infection when compared with UV-P3 was observed in the present study may contribute to the attenuated generation of antiviral immune response of the host." (PMID 21269456, 2011).